SLC1A3 (solute carrier family 1 member 3)
Description:
Sodium-dependent, high-affinity amino acid transporter that mediates the uptake of L-glutamate and also L-aspartate and D-aspartate. Functions as a symporter that transports one amino acid molecule together with two or three Na(+) ions and one proton, in parallel with the counter-transport of one K(+) ion. Mediates Cl(-) flux that is not coupled to amino acid transport; this avoids the accumulation of negative charges due to aspartate and Na(+) symport. Plays a redundant role in the rapid removal of released glutamate from the synaptic cleft, which is essential for terminating the postsynaptic action of glutamate (By similarity).
Synonyms: GLAST-1; EAAT1; GLAST; GLAST1; EA6
Tractability: Small molecule: a structure with a bound ligand is known; a high-quality ligand is known; it belongs to a druggable protein family. Antibody: UniProt places it where antibodies can reach, with high confidence; its Gene Ontology location is reachable by antibodies, with high confidence; UniProt predicts a signal peptide or a membrane-spanning region. PROTAC: ubiquitination databases record sites on it; its protein half-life has been measured; a small molecule that binds it is known.
Target class: Transporter; Electrochemical transporter; SLC superfamily of solute carriers; SLC01 family of amino acid transporters
Gene: Protein-coding gene on chromosome 5 (36,596,588 to 36,688,335, forward strand). Ensembl gene ENSG00000079215.
Subcellular location: Cell membrane
Subcellular location (Human Protein Atlas): Nucleoli; Vesicles
Pathways (Reactome):
Neuronal System: Astrocytic Glutamate-Glutamine Uptake And Metabolism; Glutamate Neurotransmitter Release Cycle
Disease: Defective SLC1A3 causes episodic ataxia 6 (EA6)
Transport of small molecules: SLC-mediated transport of amino acids
Gene Ontology:
Molecular function: glutamate:sodium symporter activity; high-affinity L-glutamate transmembrane transporter activity; L-glutamate transmembrane transporter activity; protein binding; neutral L-amino acid transmembrane transporter activity; acidic amino acid transmembrane transporter activity; amino acid binding; glutamate binding; symporter activity
Biological process: chloride transmembrane transport; D-aspartate import across plasma membrane; L-aspartate import across plasma membrane; L-glutamate import; L-glutamate import across plasma membrane; L-glutamate transmembrane transport; potassium ion transmembrane transport; amino acid transport; chemical synaptic transmission; neurotransmitter transport; neurotransmitter uptake; transepithelial transport; transport across blood-brain barrier; cellular response to cocaine; import into cell; neutral amino acid transport
Cellular component: plasma membrane; basal plasma membrane; cytoplasmic vesicle; membrane; membrane protein complex; neuron projection; neuronal cell body; perinuclear region of cytoplasm; cell periphery; cell surface; synapse
Genetic constraint (gnomAD): Loss-of-function variants: 18 observed, 43.98 expected, observed/expected ratio (o/e) 0.41, 90% interval 0.28 to 0.61. The upper end of that interval is the gene's LOEUF score, 0.61, which puts it in group 2 of 6, group 1 being the genes least tolerant of losing a copy. Missense variants: 540 observed, 718.75 expected, observed/expected ratio (o/e) 0.75, 90% interval 0.7 to 0.81. Synonymous variants: 238 observed, 263.91 expected, observed/expected ratio (o/e) 0.9, 90% interval 0.81 to 1.
Gene-disease validity (ClinGen):
ClinGen rates the evidence that SLC1A3 causes each of these diseases.
episodic ataxia type 6 (autosomal dominant): Definitive. Episodic ataxia type 6 (EA6) is an exceedingly rare form of hereditary episodic ataxia with varying degrees of ataxia and associated findings including slurred speech, headache, confusion and hemiplegia.
Homologues: Orthologues: chimpanzee SLC1A3 (99% identical), guinea pig SLC1A3 (98% identical), rabbit SLC1A3 (97% identical), pig SLC1A3 (97% identical), dog SLC1A3 (97% identical), rat Slc1a3 (97% identical), mouse Slc1a3 (97% identical), macaque SLC1A3 (94% identical), tropical clawed frog slc1a3 (87% identical), zebrafish slc1a3a (76% identical), zebrafish slc1a3b (75% identical). Paralogues in human: SLC1A6 (67% identical), SLC1A7 (51% identical), SLC1A1 (51% identical), SLC1A2 (48% identical), SLC1A4 (43% identical), SLC1A5 (41% identical).
Diseases named in the same sentence as SLC1A3 in open-access papers:
SLC1A3 is named in the same sentence as 144 diseases in open-access papers, as found by Europe PMC text mining. Sharing a sentence is not in itself a finding about the gene and the disease. The quoted sentences say what the papers report.
schizophrenia (35 papers, 2007 to 2026). A major psychotic disorder characterized by abnormalities in the perception or expression of reality. "The SLC1 family member SLC1A3 (GLAST) has been linked to the pathogenesis of schizophrenia." (PMID 23506860, 2013). "Indeed, a few patients with episodic ataxia have been shown to carry mutations in SLC1A3, and dysregulation of SLC1A3 may also be a risk factor for schizophrenia." (PMID 30122553, 2018). "We examined the association of 39 single nucleotide polymorphisms in eight genes (GRIN2A, GRIN2B, SLC1A2, SLC1A3, SLC17A7, GRM3, GRM7, and GRM8) involved in the glutamatergic system with the development of clinical heterogeneity of schizophrenia." (PMID 36980845, 2023). "The expression levels of two glutamate-related genes, Glutamate-ammonia ligase (GLUL) and glial high affinity glutamate transporter member 3 (SLC1A3) were decreased in suicide completers with schizophrenia." (PMID 17997842, 2007). "The transport genes were the most commonly over-represented biological process in our suicide candidate gene list for schizophrenia, including the glial, high affinity, glutamate transporter (SLC1A3)." (PMID 17997842, 2007). "HOMER1, MAGI2, SLC1A3, NRG3 were associated with schizophrenia." (PMID 32993537, 2020). "In the lactate shuttle, six (55%) of the significantly altered genes (n = 11) were upregulated: GLUL, LDHC, SLC16A3, SLC1A2, SLC1A3, and SLC2A1, which were collectively expressed in schizophrenia groups at a level of 1.5× higher than in control groups (LFC = 0.58)." (PMID 39125835, 2024).
glioma (28 papers, 2012 to 2026). A benign or malignant brain and spinal cord tumor that arises from glial cells (astrocytes, oligodendrocytes, ependymal cells). "In addition to these well-established glioma markers, we identified several other proteins that have never been associated with glioma biology including (e.g., SLC1A3, CLU, LGALS3BP, ANGPTL2, CRYAB and ITGB8)." (PMID 25360666, 2014). "In these subtypes, AC-like glioma cells express some characteristic astrocyte markers, such as S100B, GFAP, SLC1A3, GLAST, and MLC1." (PMID 40243478, 2025). "In particular, noncanonical Wnt signaling (WNT5A-FZD3) might promote glioma invasion and glutamatergic signaling ((SLC1A3 + GLS)–GRIA2) is known to stimulate tumor cells growth, proliferation, and survival." (PMID 38499808, 2024).
depression (23 papers, 2013 to 2025). "SLC1A3 encodes a glutamate transporter, and its dysregulation is linked to depression and anxiety, significant risk factors for suicide." (PMID 39238930, 2024). "We conclude that SLC1A3 C3590T (rs2269272) polymorphism is associated with stress and depression in eastern Indian population studied (p = 0.0042, OR = 2.072)." (PMID 32171272, 2020). "The SNP SLC1A3 C3590T was found to be associated with stress and depression (p = 0.0042, OR = 2.072)." (PMID 32171272, 2020). "The polymorphisms in two such genes, the BDNF and SLC1A3, have been reported to be linked with either depression/stress or with suicidal behaviour." (PMID 32171272, 2020). "Therefore, presence of T allele of SLC1A3 C3590T, may predict the development of stress and depression in an individual." (PMID 32171272, 2020). "Association with stress and depression was observed only in T allele of SLC1A3 C3590T in a cohort from an eastern region of India (eastern Uttar Pradesh), suggesting that the minor allele (T) in SLC1A3 C3590T may contribute to the risk of stress and depression together." (PMID 32171272, 2020). "Additional upregulated genes included Enpp2, Atp1a2, Apoe and Slc1a3, which play a role in psychiatric conditions often related to withdrawal, such as anxiety and depression." (PMID 36534642, 2022). "The present study focuses on association of SLC1A3 C3590T, C869G and BDNF G196A in case control studies with stress and depression in an eastern Indian population." (PMID 32171272, 2020). "SLC1A3 (C3590T and C869G) and BDNF (G196A) are associated with stress and depression in adolescent population of eastern Uttar Pradesh (India), a control-case association study has been undertaken." (PMID 32171272, 2020). "Multiple mRNAs regulated by chronic corticosterone exposure in this study are reported to be changed in the same direction in human depression (e.g., downregulation of Gja1, Slc1a2, and Slc1a3)." (PMID 23966905, 2013). "Besides, SLC1A3 was also related to the development of stress and depression." (PMID 39185136, 2024). "The molecular functioning, genetic interactions and expression profiling of SLC1A3 gene was also studied, but a plausible relationship between sequence variations in SLC1A3 gene and depression, have not been studied so far." (PMID 32171272, 2020). "The present study was undertaken to test whether the known polymorphisms SLC1A3 C3590T, SLC1A3 C869G and BDNF G196A are associated or not with stress or depression in an eastern Indian population." (PMID 32171272, 2020).
epilepsy (23 papers, 2013 to 2025). A brain disorder characterized by episodes of abnormally increased neuronal discharge resulting in transient episodes of sensory or motor neurological dysfunction, or psychic dysfunction. "A heterozygous SLC1A3 missense mutation predicting arginine replacement of a proline residue in transmembrane domain 5 of hEAAT1 (P290R) was identified in a 10-year-old boy, who had suffered from episodes of ataxia, epilepsy and hemiplegia throughout his childhood." (PMID 32954283, 2020). "For example, EA and epilepsy associations include EA1 (KCNA1), EA2 (CACNA1A), EA5 (CACNB4), EA6 (SLC1A3), SCN2A, KCNA2, ATP1A3, SLC2A1, and PRRT2." (PMID 37008993, 2023). "The SOX2-bound genes that are associated with glutamate import and epilepsy were identified as Kcnj10 (Kir4.1), Slc1a2 (GLT-1), and Slc1a3 (GLAST)." (PMID 36543123, 2022).
Ataxia (17 papers, 2014 to 2025). Ataxia refers to impaired coordination of voluntary muscle movement. "A de novo dominant SLC1A3 mutation segregated with ataxia in three members of a family." (PMID 25497598, 2015). "Two patients with SLC1A3 mutations (patients 6 and 23) also exhibited typical EA2-like symptoms including recurrent ataxia, slurred speech lasting several hours and interictal nystagmus, but had late-onset in the fourth or sixth decades." (PMID 29062094, 2017). "The first EAATopathy was a genetic condition combining ataxia, hemiplegia, and seizure, called episodic ataxia type 6 (EA6), and shown to be caused by mutations in SLC1A3, the gene encoding the glial glutamate transporter EAAT1." (PMID 37538371, 2023). "EA is a clinically heterogeneous disorder characterized by recurrent spells of ataxia lasting minutes to hours which has been associated over time to a number of genes besides CACNA1A and KCNA1 (CACNB4, SLC1A3, FGF14, SLC2A1, ATP1A3, PRRT2) accounting for the majority of cases." (PMID 32823520, 2020). "In this study, we conducted next-generation sequencing in Korean EA patients to identify pathogenic mutations of five known EA genes (KCNA1, CACNA1A, CACNB4, SLC1A3, and UBR4), and explored candidate genes that cause EA as a secondary phenotype or cerebellar ataxia." (PMID 29062094, 2017).
episodic ataxia type 6 (15 papers, 2014 to 2025). "Mutations in SLC1A3 cause episodic ataxia type 6 (EA6), a genetic condition characterized by ataxia, epilepsy and hemiplegia." (PMID 33587237, 2022). "Episodic ataxia type 6 is caused by monoallelic mutations in SLC1A3, encoding for the excitatory amino acid transporter 1 (EAAT1)." (PMID 33833732, 2021). "Heterozygous variants in SLC1A3 are responsible for PxMD-SLC1A3, previously termed episodic ataxia type 6." (PMID 34177764, 2021). "SLC1A3 C869G, a missense SNP, is known to be pathogenic and mutation in this gene has been found to cause episodic ataxia type 6." (PMID 32171272, 2020). "Mutations of SLC1A3 are a cause of episodic ataxia type 6 (EA6)." (PMID 29170628, 2017). "Physiological defects have been reported to occur from changes to GLAST/EAAT1 activity with GLAST knockout mice exhibiting progressive motor incoordination and mutations in SLC1A3, the gene encoding EAAT1, being associated with episodic ataxia type 6 (EA6)." (PMID 29741614, 2018). "Two homologous mutations, which predict substitutions of prolines in the center of the fifth transmembrane helix by arginine (P289R EAAT2, P290R EAAT1), have been identified in patients with epileptic encephalopathy (SLC1A2) or with episodic ataxia type 6 (SLC1A3)." (PMID 37538371, 2023).
diabetes (14 papers, 2013 to 2026). "Diabetes caused significant decrease in the transcriptional expression of glutamate transporter SLC1A3 gene encoding GLAST protein, leading to the decreased removal of glutamate from the extracellular space, suggesting that diabetes impairs the glutamate transporter function of Müller cells." (PMID 24386591, 2013). "Decreased expression of the glutamate transporter SLC1A3 would lead to decreased removal of glutamate from the extracellular space, suggesting that diabetes impairs this function of Müller cells." (PMID 23878504, 2013). "In addition to SLC1A3, the expression of VGLUT1 and VGLUT2 transcripts was also altered by STZ-induced diabetes." (PMID 23878504, 2013). "Literature data have previously shown isolated patch clamp studies of glutamate transporter (SLC1A3 or GLAST) in Müller cells exposed to hyperglycemia, confirming dysfunction of this transporter, with a significant decrease in its activity after 3 mo of STZ-induced diabetes." (PMID 41266111, 2026).
episodic ataxia (13 papers, 2011 to 2023). "Changes in glial Cl− homeostasis caused by mutations in SLC1A3 that encodes EAAT1 play a central role in the disease pathogenesis of certain forms of episodic ataxia, an inherited neurological conditions." (PMID 34073593, 2021). "SLC1A3 - The observation of a missense mutation P290R in SLC1A3 in a single patient with alternating hemiplegia, episodic ataxia, and seizures, does not qualify SLC1A3 as a bona fide hemiplegic migraine gene either." (PMID 32503413, 2020).
Alzheimer disease (12 papers, 2010 to 2026). A progressive, neurodegenerative disease characterized by loss of function and death of nerve cells in several areas of the brain leading to loss of cognitive function such as memory and language. "Genes such as SLC1A3, FOXP1, and MS4A6A, associated with inflammatory response, and microglia in aging and Alzheimer's disease, had positive average coefficients among the microglia clock feature genes." (PMID 40878446, 2025). "We found that NSUN7, SLC6A8, CXCL1 and LCN8 were significantly different in groups B compared to A, and SLC1A3 and LCN8 were significantly different in groups C compared to A. NSUN7, a m5C RNA methyltransferase gene, is differentially expressed in Alzheimer's disease patients." (PMID 39185136, 2024).
autism (11 papers, 2012 to 2024). Persistent deficits in social interaction and communication and interaction as well as a markedly restricted repertoire of activity and interest as well as repetitive patterns of behavior. "A gene duplication of SLC1A3 has also been reported as a possible risk factor for autism and attention deficit/hyperactivity disorder–like behaviour." (PMID 29741614, 2018). "So far, five different brain disorders have been associated with SLC1A3 mutations: EA, migraine; Tourette syndrome, attention-deficit hyperactivity disorder and autism." (PMID 32954283, 2020). "However, there were a few regions outside the deletion region that exhibited significant differential methylation; of interest were changes in the gene SLC1A3 (corrected P = 4.71E−07, mean DNA methylation beta value Δ − 0.06), which has previously been implicated in Autism." (PMID 30021660, 2018). "SLC1A3, which is similar to SLC1A2, involved in rapid glutamate removal from the synaptic cleft and had >4-fold higher expression in astrocytes vs. neurons, was also decreased by 90% only in the astrocytes of patients with autism (p = 0.002)." (PMID 38994948, 2024).
breast carcinoma (11 papers, 2010 to 2025). "In this regard, SLC1A3 (EAAT1) has been identified to contribute to asparaginase resistance in prostate and breast cancer in which combined treatment with asparaginase and EAAT1 chemical inhibition restrains cancer cell proliferation and tumor progression." (PMID 36457557, 2022). "Next, we employed 4T1, a highly malignant mouse breast cancer cell line, for the assessment of the influence of SLC1A3 on ASNase efficacy in vivo." (PMID 31523835, 2019). "We identified SLC1A3, an aspartate/glutamate transporter, as a novel contributor to ASNase resistance, as well as tumor initiation and progression in a mice model for breast cancer metastasis." (PMID 31523835, 2019). "We investigated the correlations between SLC1A3 mRNA level, aspartate uptake, and sensitivity to ASNase treatment in a panel of prostate and breast cancer cell lines." (PMID 31523835, 2019). "For example, a resent study reported that silencing FN1 inhibits YAP1/Hippo pathway activation by enhancing YAP1 phosphorylation, reduces aspartate uptake and utilization via SLC1A3, and suppresses breast cancer cell proliferation, invasion, migration and promotes apoptosis." (PMID 39218967, 2024). "Importantly, one ofthese two glial-specific glutamate transporters (Slc1a3) is alsotranscriptionally over-expressed in the stroma of human breast cancer patients." (PMID 20442453, 2010). "Therefore, we next assessed whether SLC1A3 expression could negate the inhibitory effect of ASNase on cancer cell invasion in a mouse metastasis model for human breast cancer cells as described recently." (PMID 31523835, 2019). "Using an engineered metastatic niche, we identified a 9‐gene signature (Dhx9, Dusp12, Fhl1, Ifitm1, Ndufs1, Pja2, Slc1a3, Soga1, Spon2) that successfully delineated metastatic breast cancer from nonmetastatic breast cancers including an invasive cell line without metastatic potential." (PMID 38193115, 2024). "Hypoxia did not induce SLC1A1 and SLC1A3 mRNA in two breast cancer cell lines." (PMID 25326682, 2014). "Since many cells cannot take up exogenous aspartate due to no or low expression of the aspartate transporter, SLC1A3, we also expressed SLC1A3 prior to aspartate supplementation to levels comparable to MDA-MB-468 breast cancer cells." (PMID 32645038, 2020).
glioblastoma (11 papers, 2015 to 2026). The most malignant astrocytic tumor (WHO grade IV). "By leveraging AI-based foundation models alongside robust biological validation, we uncovered a novel mechanism of vascular-mediated immune evasion, highlighting SLC1A3 as a highly promising therapeutic target to reprogram the glioblastoma microenvironment and restore anti-tumor immunity." (PMID 42112375, 2026).